TRPA1 (transient receptor potential cation channel subfamily A member 1)
Diseases named in the same sentence as TRPA1 in open-access papers (continued):
Sharing a sentence is not in itself a finding about the gene and the disease.
migraine (continued). "Further evidence establishing TRPA1 as a therapeutic target for migraine comes from in vivo and in vitro pre-clinical studies." (PMID 37175602, 2023). "Nearly two decades later, isopetasin, an active component of butterbur, was shown to have a desensitizing effect on TRPA1, which effect is suggested to be responsible for the anti-migraine action." (PMID 36982450, 2023). "TRPA1 is sensitive to oxidative stress and is also the target of emerging drugs involved in migraine prevention." (PMID 37039840, 2023). "TRPA1 is highly co-expressed with TRPV1 and is associated with familial pain syndrome and umbellulone (a naturally occurring migraine inducer)." (PMID 36831105, 2023). "We also present arguments for the importance of epigenetic effects in a perspective TRPA1-targeting anti-migraine therapy." (PMID 37326902, 2023). "Preclinical and clinical evidence has highlighted the role of the activation of TRP channels (mainly TRPA1) in the pathophysiology of various chronic pain (such as migraine) by promoting CGRP release." (PMID 37858040, 2023). "Focusing on migraine, here we review some migraine medications, which appear to work by the desensitization of the TRPA1." (PMID 36982450, 2023). "TRPV1 and TRPA1 channels are expressed by peptidergic trigeminal neurons, which synthesize and store the main migraine mediator CGRP." (PMID 37123270, 2023). "Nonetheless, it will be necessary to define the precise mechanisms through which TRPA1 channels mediate the neuroinflammatory response in the context of migraine-like pain." (PMID 36430567, 2022). "In the present study, we delineated the relationship between TRPA1 channels and glial activation in trigeminal hyperalgesia induced in animal models of migraine." (PMID 36430567, 2022). "The same missense variants were not present in any of the ICG genes in painful- and painless-DN, with the exception of migraine-related KCNK18 variants c.414_415del and c.361dup and TRPA1 c.352C>G." (PMID 35806193, 2022). "The high intracellular concentration of iron in glial cells can trigger oxidative stress—known to be involved in migraine pathophysiology —which, in turn, can activate and stimulate TRPA1 channels." (PMID 36430567, 2022). "Glyceryl trinitrate, which can induce migraine attacks in patients, promotes NO release, which triggers pain-like responses through TRPA1." (PMID 36614146, 2022). "Several migraine triggers can activate TRPA1, and some medications already used to treat migraine can desensitize or inhibit TRPA1." (PMID 36614146, 2022). "The aim of this study was to investigate the relationship between TRPA1 channels and glial activation in the modulation of trigeminal hyperalgesia in preclinical models of migraine based on acute and chronic nitroglycerin challenges." (PMID 36430567, 2022). "We showed that TRPA1 antagonism is effective for reducing migraine-like pain via an interference with inflammatory pathways, thus confirming the links among TRPA1, pain, and neuroinflammation." (PMID 36430567, 2022). "TRPA1 can be activated by a variety of exogenous and endogenous irritants, some of which are migraine triggers in people with migraine, including umbellulone (UMB) and nitric oxide (NO)." (PMID 34830154, 2021). "In this study, we explored the potential role of Src family kinases (SFK) in TRPA1-mediated migraine pathophysiology in trigeminal ganglion (TG), the key anatomical region for migraine pain transmission from periphery to brain." (PMID 34488620, 2021). "Background and objective: TRPA1 is a promising therapeutic target in migraine by responding to migraine triggers and regulating migraine pathogenesis." (PMID 34488620, 2021). "The TRPA1 antagonism has been reported to attenuate the trigeminal pain and migraine-like behaviours in different rodent models of facial pain with a similar duration of antinociceptive effect." (PMID 34451927, 2021).
migraine (continued). "Taken together, SFKs-transmitted TRPA1 signaling is least likely to occur via their direct interaction in migraine pathogenesis." (PMID 34830154, 2021). "Taken together, our data unravel for the first time that TRPA1-meidated Src Family Kinases activity facilitates CSD susceptibility and trigeminovascular system sensitization, thereby contributing to migraine progression." (PMID 34830154, 2021). "TRPA1 channels have also been recounted as an underlying cause of cortical spreading depression (CSD), which further acts as a base of migraine pain." (PMID 34912298, 2021). "Transient receptor potential ankyrin 1 (TRPA1) plays a role in migraine and is proposed as a promising target for migraine therapy." (PMID 34830154, 2021). "Activated TRPA1 can induce pain signaling and neurogenic inflammation, symptoms featuring in migraine attacks." (PMID 34959985, 2021). "Transient receptor potential ankyrin 1 (TRPA1) has drawn increasing attention to play a role in migraine pathogenesis." (PMID 34830154, 2021). "For these reasons, TRPA1 has been studied as a valuable therapeutic target for headache and migraine treatment." (PMID 34451927, 2021). "Activation of TRPA1 channels triggers migraine, while its desensitization helps in reducing migraine pain." (PMID 34912298, 2021). "Although the molecular mechanism underlying how SFKs transmit signaling from TRPA1 in migraine is not fully known, here we identify that PKA serves as an intermediate molecule, transmitting signaling from TRPA1 to SFKs facilitating TVS sensitization." (PMID 34830154, 2021). "Some anti-migraine drugs, including sumatriptan and valproic acid, can attenuate the TRPA1-mediated migraine-related allodynia and meningeal blood flow." (PMID 34830154, 2021). "Many TRPA1 agonists that are linked to the release of SP and CGRP have also been shown to induce migraine or headache behaviors." (PMID 33193423, 2020). "Given that TRPA1-deficient mice lack allodynia and TRPA1 channel activation facilitates the development of neuropathic pain, Collectively, anti-TRPA1 therapies are likely to form a preventive strategy for migraine prophylaxis." (PMID 30841847, 2019). "The other key study leading to increased interest in TRPA1 and migraine was the finding that this channel mediates the vasodilatory response to inhalation of acrolein." (PMID 30970581, 2019). "One such emerging drug target for migraine prevention involves the transient receptor potential ankyrin type 1 (TRPA1)." (PMID 30841847, 2019). "Our study suggest that TRPA1 plays an important role in migraine pathogenesis through central mechanism." (PMID 30841847, 2019). "This study aimed to understand their mechanisms in migraine by investigating the role of TRPA1 in cortical spreading depression (CSD) in vivo and exploring how reactive oxygen species (ROS)/TRPA1/CGRP interplay in regulating cortical susceptibility to CSD." (PMID 30841847, 2019). "The results of this study indicate that CGRP, COX-2, TRPV1, and TRPA1 immunoreactive cells increased in the TG in the NTG-induced migraine rat model, and these increases were reduced by auricular ES pretreatment." (PMID 31885641, 2019). "In line with this, a number of migraine triggers have been identified as TRPA1 activators and a number of drugs used for migraine treatment desensitize or inhibit TRPA1." (PMID 30388732, 2018). "Among the candidates is nitroglycerin-induced migraine in which TRPA1 is directly driven by nitric oxide." (PMID 30388732, 2018). "Clinical and experimental studies have pointed to the possible involvement of the transient receptor potential ankyrin type-1 (TRPA1) channels in migraine pain." (PMID 28884307, 2017). "Clinical and experimental studies have pointed to the possible involvement of the TRPA1 channels in migraine pain." (PMID 28884307, 2017).
migraine (continued). "Activation of TRP channels, such as TRPV1 and TRPA1, has been reported to induce the trigeminal calcitonin gene-related peptide pathway, which mediate neurogenic inflammation, thus leading to the migraine attacks." (PMID 28649203, 2017). "In this study, we aimed to further investigate the role of these channels in an animal model of migraine using a novel TRPA1 antagonist, ADM_12, as a probe." (PMID 28884307, 2017). "Although a number of different animal models of migraine have been developed (e.g., dural inflammatory soup, systemic nitroglycerin), we used microinjection of the TRPA1 agonist allyl isothiocyanate (AITC) onto the dura to generate migraine pain." (PMID 28091820, 2017). "Recent studies have demonstrated a potential role of transient receptor potential vanilloid type-1 receptor (TRPV1) and transient receptor potential ankyrin 1 (TRPA1) channels in the pathophysiology of migraine pain." (PMID 26184313, 2015). "The existence of a potential link to migraine is indicated by the observation that various volatiles trigger migraine, likely via TRPA1-dependent mechanisms." (PMID 24205061, 2013). "Parthenolide may produce the anti-migraine activity by acting as a partial agonist to TRPA1, desensitizing the TRPA1 channel to any stimulus, which resulted in the inhibition of CGRP release." (PMID 40005953, 2025). "In a nitroglycerin‐induced acute migraine mouse model, the selective TRPA1 antagonist ADM_12 significantly attenuates microglial and astrocytic activation within the trigeminal nucleus caudalis (TNC), and reduces satellite glial cell activation in the TG, consequently reversing hyperalgesia." (PMID 41399206, 2025). "Understanding these gasotransmitters’ roles may provide novel therapeutic targets for migraine management, particularly through modulation of TRPA1-CGRP signaling and oxidative stress pathways." (PMID 40391079, 2025). "Owing to its irritant-sensing properties, TRPA1 has gained considerable interest as a pharmacological target in diseased conditions to control symptoms such as pain, itch, cough, or neurogenic inflammation, including migraine." (PMID 41118703, 2025). "A recent study has shown that TRPA1 is closely involved in the pathogenesis of migraines." (PMID 39273183, 2024). "Several irritants, including those related to migraine triggers, may activate TRPA1 in nociceptors, evoking action potential signaling pain." (PMID 39064963, 2024). "Experimental data in rats suggest that after CSD, oxidative stress spreads downstream within the trigeminal nociceptive system and could be involved in the coupling of CSD with the TRPA1-mediated activation of the trigeminovascular system in migraine." (PMID 39064963, 2024). "Such activation may be hampered by TRPA1 antagonists, making the molecule a druggable target in migraine and other disorders with pain and inflammation in their pathophysiology." (PMID 39064963, 2024). "Therefore, it is important to recognize molecular pathways leading from oxidative stress to migraine mediated by TRPA1." (PMID 39064963, 2024). "TRPA1 may regulate blood flow in brain vessels in response to inflammatory and oxidative stress, which may contribute to migraine development." (PMID 39273183, 2024). "Finally, we review the arguments that TRPA1 can be a “missing element” linking oxidative stress with migraine." (PMID 39064963, 2024). "In migraine, TRPA1 regulates cerebral blood flow and pain, suggesting that the blockade of TRPA1 may be a therapeutic approach." (PMID 39273183, 2024). "Moreover, TRPA1 in trigeminal neurons can be activated by several factors that are considered migraine triggers." (PMID 39064963, 2024). "Furthermore, some chemicals projected to be used or used in migraine treatment desensitize or inhibit TRPA1." (PMID 39064963, 2024).
migraine (continued). "In this narrative review, we present information on the role of oxidative stress in migraine pathogenesis and provide arguments that TRPA1 may be “a missing link” between oxidative stress and migraine and therefore a druggable target in this disease." (PMID 39064963, 2024). "In particular, TRPA1-mediated consequences of oxidative stress-related migraine triggers may significantly contribute to migraine pathogenesis." (PMID 39064963, 2024). "TRPA1 agonists can stimulate the release of migraine-related neuropeptides, including CGRP and substance P (SP) that may contribute to neurogenic inflammation." (PMID 39064963, 2024). "In addition, an endogenous product, 4-hydroxynonenal, which is associated with several chronic diseases, has been shown to act as a potential activator of TRPA1, supporting the relevance of TRPA1-activation in chronic pain disorders such as migraine." (PMID 36982450, 2023). "In conclusion, epigenetic connections of TRPA1 may play a role in efficacy and safety of anti-migraine therapy targeting TRP channels or CGRP and they should be further explored for efficient and safe antimigraine treatment." (PMID 37326902, 2023). "The involvement of the TRPA1 receptor in migraine headaches is proposed by the fact that TRPA1 may be a target of some migraine-triggering factors." (PMID 36982450, 2023). "On the other hand, the TRPA1 channel has attracted attention due to its ability to transduce a multitude of chemical agents such as formaldehyde and cigarette smoke, many of which are also common migraine triggers." (PMID 37370051, 2023). "TRPA1 is plentifully expressed in primary sensory neurons and is considered sensors of chemical-, heat-, and mechanical-induced pain, playing a major role in migraine pain." (PMID 37326902, 2023). "Furthermore, the data above not only support the putative role of TRPA1 in the pathophysiology of migraine but propose the potency of TRPA1 inhibition in anti-migraine therapy." (PMID 36982450, 2023). "It was shown that the commonly used TRPA1 agonist AITC and umbellulone also promoted the spread of CSD, indicating not only the involvement of TRPA1 in migraine with aura but also the sensitizing act of TRPA1 activation in the pathomechanism of the aura phenomenon." (PMID 36982450, 2023). "Numerous studies have shown that meningeal TRPA1 may mediate migraine responses to environmental stimuli, one of the most common triggers of migraine." (PMID 37039840, 2023). "These channels respond to stimuli involved in migraine pathogenesis and TRPA1 is of a special interest in this regard as it is reported to be a link between stimulants of headache pain and migraine as well as mediate the vasodilatory response to environmental irritants evoking headache." (PMID 37326902, 2023). "NTG, a migraine-inducer, displays a high selectivity toward TRPA1 over other TRP channels." (PMID 37326902, 2023). "According to the reviewed data, the modification of TRPA1 activity in the development of migraine-related hypersensitivity may be considered one of the main directions for migraine research." (PMID 36982450, 2023). "ROS and CGRP, TRPA1, and TRPV1 can interact to cause migraine." (PMID 37123270, 2023). "Inhibition of ROS and deactivation of TRPA1 channels may have therapeutic benefits in the prevention of stress-induced migraine via CGRP." (PMID 37123270, 2023). "This study showed that TRPA1 was expressed in a significant proportion of dural afferents, and activation of meningeal TRPA1 induced behaviors consistent with those observed in patients during migraine attacks." (PMID 37326902, 2023). "There are some key discoveries relating TRPA1 to migraine pathogenesis." (PMID 37326902, 2023). "However, the proposed therapeutic potential of TRPA1 in headache disorders is supported by the fact that sumatriptan, the iconic anti-migraine medicine, has been recently demonstrated to inhibit TRPA1-mediated vasodilation in meningeal tissues." (PMID 36982450, 2023).
migraine (continued). "TRPA1, along with transient receptor potential cation channel subfamily V member 1 (TRPV1), TRPV4, and transient receptor potential cation channel subfamily M member 8 (TRPM8), are most consistently reported to associate with migraine among all TRP channels." (PMID 37326902, 2023). "As TRPA1 and CGRP are both implicated in migraine pathology (see Section 1,), inhibition of AITC-evoked CGRP release might offer potential as a therapeutic intervention for this debilitating condition." (PMID 36674850, 2023). "Obviously, umbellulone is not the only one environmental irritant that may be involved in migraine attack, so TRPA1 may be generalized as a mediator of the migraine-related effects of such substances." (PMID 37326902, 2023). "Indeed, it has been shown that multiple SDs can increase phosphorylation of Src family kinases (SFKs) to drive TRPA1 signaling and sensitize trigeminovascular pathways in migraine." (PMID 37924146, 2023). "TRPA1 is also involved in neurogenic inflammation, important in migraine pathogenesis." (PMID 37326902, 2023). "Indeed, even though the ability of ADM_12 to inhibit the TRPA1 channels activity has previously been reported, it would be of great relevance to directly investigate the activity and functionality of TRPA1 channels in relation to the present migraine models." (PMID 36430567, 2022). "The role of TRPA1 channels in migraine pathogenesis is supported by multiple pieces of evidence." (PMID 36430567, 2022). "First, exogenous compounds that are TRPA1 agonists can trigger migraine attacks." (PMID 36430567, 2022). "TRPA1 channels have been found to play a cardinal role in NPDs (like depression and anxiety), Alzheimer’s disease, Huntington’s disease, multiple sclerosis, migraine, and age-related cognitive impairment in different rodent models." (PMID 34912298, 2021). "In other words, TRPA1 might be a bridge between oxidative stress and neuroinflammation in migraines." (PMID 34444772, 2021). "Therefore, it is likely that SFKs can transmit TRPA1 signaling, contributing to migraine pathogenesis." (PMID 34830154, 2021). "An alternative explanation that may underlie SFKs transmit signaling from TRPA1 in migraine involves protein kinase C (PKC) as this enzyme regulates TRPA1 activity and SFKs activity and PKC plays a part in TRPA1-mediated nociception." (PMID 34830154, 2021). "In particular, intranasal or dural application of TRPA1 agonists increases meningeal blood flow, neurogenic inflammation, nociceptive behaviors, intraganglionic transmission and release of a known target for migraine prevention and therapy, CGRP." (PMID 34830154, 2021). "Moreover, the migraine-like mouse model induced by systemic GNT administration was able to increase H2O2 and 4-HNE levels in trigeminal ganglion and caused PMA via TRPA1 activation." (PMID 34451927, 2021). "These anti-oxidants might lead to reduced TRPA1 activation through the inhibition of oxidative stress generation, attenuating the migraine-like symptoms." (PMID 34451927, 2021). "TRPA1 undergoes oxidative stress and initiates a neuroinflammatory response in migraines." (PMID 34444772, 2021). "Migraine ”ionopathy” likely derives from one or multiple channelopathies which may be inherited e.g., mutations in CACNA1A and TRPA1, or result from the effects of toxic environmental factors." (PMID 33799975, 2021). "This evidence underpins TRPA1 as one of the most promising targets for migraine therapy." (PMID 34830154, 2021). "Another TRP that could be targeted for its analgesic effects in humans is TRPA1, which is activated by migraine-inducing agents, suggesting that antagonists may help reduce neuropathic pain and migraine." (PMID 32824721, 2020). "Activation of TRPA1 on TG nerves via environmental irritants contributes to this release of SP and CGRP along with increased meningeal vasodilation, which are implicated in migraine pathophysiology." (PMID 33193423, 2020).